ENSG00000272921 (novel protein)
Gene: Protein-coding gene on chromosome 12 (4,604,944 to 4,662,643, forward strand). Ensembl gene ENSG00000272921.
Genetic constraint (gnomAD): Missense variants: 78 observed, 64.19 expected, observed/expected ratio (o/e) 1.22, 90% interval 1.01 to 1.47. Synonymous variants: 29 observed, 28.13 expected, observed/expected ratio (o/e) 1.03, 90% interval 0.77 to 1.4.